IL6 (interleukin 6)
Diseases named in the same sentence as IL6 in open-access papers (continued):
Sharing a sentence is not in itself a finding about the gene and the disease.
Cognitive impairment (continued). "Intraperitoneal injection of hemin induced cognitive impairment, increase of CD91 + cells, up-regulation of TNF-α and IL-1β, down-regulation of IL-6, activation of microglia, and activation of the TLR4/MyD88/NF-κB signaling pathway in rat brain." (PMID 38183122, 2024). "Several studies have found elevated IL-6 concentrations in brain tissue and peripheral blood in a variety of disorders, including AD, Lewy body dementia, and vascular dementia, suggesting that inflammatory mechanisms may be involved in the development of cognitive impairment." (PMID 39376966, 2024). "In the current study, compared with the Control group, the hippocampal levels of IL-1β, IL-6, and TNF-α were increased in the MLPS group, which likely contributed to the cognitive impairment induced by maternal LPS exposure." (PMID 38074521, 2023). "Among the key targets, increased levels of the inflammatory cytokines interleukin-6 (IL6), tumor necrosis factor (TNF), and interleukin-1β (IL1B) all independently contribute to cognitive impairment." (PMID 37233418, 2023). "Cognitive impairment in patients with schizophrenia has been related to gray-matter volume (GMV) reduction in key brain regions and increased interleukin-6 (IL-6) levels." (PMID 37838729, 2023). "The levels of inflammatory cytokines (interleukin-1 beta (IL-1β), interleukin-6 (IL-6), interleukin-8 (IL-8), and tumour necrosis factor-alpha (TNF-α)) were measured using an assay method and compared with the subjective cognitive impairment." (PMID 39484178, 2023). "For example, pro-inflammatory factors such as leptin, IL-6, TNF-α which are secreted by adipocytes can cross the BBB and lead to neuroinflammation, which plays a role in cognitive impairment and AD." (PMID 37457589, 2023). "That study also explored the potential role of inflammatory proteins such as CD70 which have previously been associated with central nervous system (CNS) inflammation, as both IL‐6 and CD70 were raised in patients with cognitive impairment at 1‐year follow‐up." (PMID 37904690, 2023). "We found that cognitive impairment-like behaviors and TNF-α and IL-6 expression were higher in the hippocampus of aged mice than in those of young mice." (PMID 37872562, 2023). "In the current study, OVX induced cognitive impairment in mice and increased oxidative stress, serum CORT level, and expression of the inflammatory-related genes IL-1β, IL-6, and TNF-α in the frontal cortex and hippocampus." (PMID 35807554, 2022). "Multivariate analysis showed that 95% CI of cytokines IL‐6, IL‐1β, TNF‐α, IFN‐α, and cognitive function was high, indicating a significant correlation between cognitive impairment and these cytokines." (PMID 34939360, 2022). "For example, after peripheral surgery, the concentration of IL-6 increases in peripheral blood and the structure of the BBB breakdown, thereby inducing cognitive impairment in mice." (PMID 36353359, 2022). "miR-122-5p inhibition prevents cognitive impairment, neuronal damage, microglia activation, and production of TNF-a, IL-6, and IL-1ß in hippocampus." (PMID 35955439, 2022). "In this study, the levels of 5-HT, GABA, and BDNF in the blood of premature rats with cognitive impairment decreased, while that of GR, CRH, IL-6, and TNF-α increased, in comparison to the control group." (PMID 36061856, 2022). "We then compared the serum levels of soluble factors including 5-HT, GABA, BDNF, GR, CRH, IL-6 and TNF-α in preterm rats from the normal control group and cognitive impairment group." (PMID 36061856, 2022). "Inflammation has been implicated as a trigger of ADHD, and gastrodin has been proved to have anti-inflammatory pharmacological effects, which can alleviate cognitive impairment by lessening TNF-α and IL-6 levels." (PMID 36133787, 2022).
Cognitive impairment (continued). "We used traumatic surgical model and burns model in mice and found that peripheral inflammatory cytokines, including IL-6 and IL-1β, were main factor leading to the disruption of BBB and thus cognitive impairment." (PMID 36353359, 2022). "The presence of long-lasting increments in pro-inflammatory cytokines in the hippocampus, such as Il-6, IL-1β, and TNF-α, has led to the implication of neuroinflammation in brain aging and cognitive impairments." (PMID 35866081, 2022). "Higher DII scores, also known as larger inflammatory potential of the diet, have been related to increased levels of inflammatory biomarker including IL-6, CRP, and TNF-α, thus linking to cognitive impairment." (PMID 36688153, 2022). "On the one hand, abnormal Tregs can induce more production of the pro-inflammatory factors (IL-6, IL-17, and IFN-γ), then aggravate the neuroinflammation and cognitive disorder." (PMID 34912208, 2021). "Activated microglia were found to participate in the secretion of pro-inflammatory cytokines, including IL-1β, IL-6, TNF-α, and TGF-β, thus aiding the development of cognitive impairment in individuals with neurological disorders." (PMID 35153660, 2021). "Residual schizophrenia, and its most known manifestation (cognitive impairment), is characterized by a typical biochemical decrease in BDNF and TNF-α, and at the same time an increase in IL-2, IL-6, and IL-8." (PMID 34434228, 2021). "Some studies discover that the increased expression levels of IL-6 and IFN-γ are bound up with deteriorating cognitive deficits in patients with VCI." (PMID 34912208, 2021). "Finally, sevoflurane did not cause cognitive impairment in IL-6 KO mice from P31 to P38." (PMID 34589883, 2020). "Melatonin and rapamycin significantly ameliorated the isoflurane-induced cognitive impairment and also led to a decrease in the melatonin levels as well as the expression levels of TNF-α, IL-1β, IL-6, and p-mTOR in the hippocampus." (PMID 31803045, 2019). "In our present study, the degree of cognitive impairment following TZB therapy and the compensatory effects of ATV were confirmed using a passive avoidance test and measuring the levels of IL-6, IL-1β, and TNF-α." (PMID 30754707, 2019). "Therefore, cognitive impairment during TZB therapy may be explained by increased IL-6 levels." (PMID 30754707, 2019). "Expression of IL-6, IL-8, and TNF-α in the two groups was reduced significantly with variation of the clinical scales of cognitive impairment." (PMID 29853963, 2018). "As we reviewed, the IL-6 plays significant role in disease genesis and progression, so the use of specific inhibitors may not only be beneficial for exacerbation and alleviation of positive symptoms, but may attenuate cognitive impairment in patients with schizophrenia." (PMID 29163240, 2017). "IL-6 plays significant role in disease genesis and progression, and the use of specific inhibitors may not only be beneficial for exacerbation and alleviation of positive symptoms, but in particular to possible attenuation of cognitive impairment in patients with schizophrenia." (PMID 29163240, 2017). "Given that recent studies have suggested that isoflurane may induce neuroinflammation which may be associated with cognitive impairment, we examined with Western blot assays the effects of isoflurane and propofol on the proinflammatory cytokines, TNF-α, IL-1β and IL-6, in the cortex at P7." (PMID 24932894, 2014). "Weak to moderate correlations were observed between IL-1β, IL-6, TNF-α levels, and different degrees of cognitive impairment." (PMID 24339912, 2013). "The administration of minocycline in 8-month-old 3xTg-AD mice was also shown to prevent cognitive deficits and to decrease insoluble Aβ and soluble fibrils via the reduction of inflammatory agents such as GFAP, TNF-α and IL-6." (PMID 22339795, 2012).
Cognitive impairment (continued). "In light of the pivotal role of immune parameters (e.g., CXCL13, IL21, IL6, and CCL20) in the distinct microbial composition at early liver disease stages and in general with cognitive impairment, we determined which specific bacterial taxa are related to these patterns." (PMID 41035890, 2025). "Proinflammatory cytokines from the periphery, such as IL-6 or CX3CL1, could modify the response of microglia, increasing the proinflammatory environment and cognitive impairment." (PMID 40004217, 2025). "They further found that OBB or OBB‐NC administration can reduce long‐term neuropsychiatric complications such as anxiety, depression, and cognitive impairment, as well as inhibit the HMGB1‐mediated TLR4/NF‐κB pathway in microglia by downregulating the levels of TLR4, HMGB1, NF‐κB, TNF‐α and IL‐6." (PMID 40824273, 2025). "Elevated levels of IL-6, TNF-α, and C-reactive protein (CRP) have been documented in individuals with LDs, suggesting that immune dysregulation may contribute to cognitive impairments." (PMID 40150106, 2025). "IL-6 mediates the association between long-lasting T2DM and AD biomarkers in middle-aged and older community-dwelling adults without previously diagnosed cognitive impairment." (PMID 40606939, 2025). "Another significant mechanism is immune dysregulation and neuroinflammation, where environmental toxins activate pro-inflammatory cytokines such as IL-6 and TNF-α, which in turn lead to chronic neuroinflammation, worsening ASD-related behavioral and cognitive deficits." (PMID 40442748, 2025). "In addition, sleep deprivation significantly elevated the levels of proinflammatory cytokines including IL‐1β, IL‐6, and TNF‐α in the hippocampus and resulted in cognitive impairment during the novel object recognition test." (PMID 38688894, 2024). "Indeed, inflammatory cytokines, such as interleukin 1-β (IL-1β), interleukin-6 (IL-6), and tumor necrosis factor-alpha (TNF-α), are increased in AD and mild cognitive impairment (MCI) patients." (PMID 39057049, 2024). "Patients with overall cognitive impairment at year 2 tended to be more likely to have a high IL-6 level (n = 43, 81%) than patients without it (n = 99, 68%; p = 0.10)." (PMID 38840166, 2024). "Additionally, IL-6 and the CD70 molecule were significantly increased in the moderate with cognitive impairment cluster compared with the mild cluster." (PMID 37368949, 2024). "Overall, these findings demonstrate that early‐life alcohol exposure triggers an inflammatory microglial response involving the release of IL‐6, which activates JAK/STAT signaling, leading to hippocampal neuronal apoptosis and developmental/cognitive impairments." (PMID 40625899, 2024). "Moreover, increased levels of interleukin-6 (IL-6) and C-reactive protein (CRP) have been observed in long sleepers, suggesting a link between prolonged sleep, inflammation, and cognitive impairment." (PMID 39839310, 2024). "To date, this is the first study that has studied the relationship between salivary IL-6 and sleep in institutionalized elderly people with and without cognitive impairment." (PMID 37489445, 2023). "Nevertheless, cognitive impairment was not correlated to IL-6, IL-8, or IL-10 at any time point (all P>0.05)." (PMID 37878890, 2023). "This is the first study that has studied the relationship between salivary IL-6 and sleep in institutionalized elderly people with or without cognitive impairment." (PMID 37489445, 2023). "A recent study showed that LDL -C activates the secretion of pro- inflammatory mediators such as tumor necrosis factor alpha and interleukin-6 and decreased the BBB membrane injury, a contributory factor to the development and progression of cognitive impairment." (PMID 37098461, 2023). "In addition, administration of echinomycin rescues cognitive deficits, ameliorates HIF-1α and BNIP3L-mediated neuronal pyroptosis and damaged mitochondrial structures, and decreases the expression of TNF-α and IL-6 in the hippocampus." (PMID 36569834, 2022).
Cognitive impairment (continued). "The levels of 5-HT, GABA, and BDNF in the blood samples from the premature rats with cognitive impairment were significantly lower than that from the normal control group, while the serum levels of GR, CRH, IL-6, and TNF-α were significantly up-regulated in rats with cognitive problem." (PMID 36061856, 2022). "While IL-6 is elevated in mTBI in adult studies, it has not correlated with cognitive impairment, a common component of post concussive syndrome." (PMID 35130911, 2022). "In our data, the correlation coefficients between SOD and cognitive score (MMSE, MoCA) were not high, and the differences in inflammatory indexes (ESR, CRP, IL-6) between patients with and without cognitive impairment were small." (PMID 35296032, 2022). "It is worth noting that G-CSF is not the only key molecular regulating the cognitive deficits due to Pb exposure, which was partly demonstrated by the consistent performance of IL-6 and TNF-α cytokines, as well as the ensuing crucial incidents of microgliosis." (PMID 35928850, 2022). "Our results show that CLP-induced hippocampus-dependent cognitive deficits were accompanied with increased HIF 1a and decreased BNIP3L, increased protein levels of TNF-α, IL-6, and IL-β, and damage to mitochondrial structures and neuronal apoptosis in the hippocampus." (PMID 36569834, 2022). "The third major finding of this study is that the latent vector score extracted from the IL-6/IL-23/Th17 data was considerably greater in MNP than SNP, with a difference of more than one standard deviation, and predicted cognitive deficits and the severity of the phenotype of schizophrenia." (PMID 36256663, 2022). "There is a positive correlation between the concentration of IL-6 in the blood and negative and positive symptoms, as well as the overall psychopathological presentation and cognitive deficits." (PMID 34501305, 2021). "Notably, it has been demonstrated that onjisaponin B can prevent cognitive impairment in d-gal induced aging in rats by regulating inflammatory mediators (TNF-α, IL-6, and IL-1β) and oxidative stress-related indicators (MDA, SOD, GSH, and GSH-PX)." (PMID 33878733, 2021). "Finally, patients with PD and cognitive deficit (MMSE < 26) (n = 51) exhibited significantly increased plasma EV pro-IL-1β, IL-6, TNF-α, and IL-10 levels and a significantly decreased TGF-β1 level." (PMID 33803292, 2021). "With respect to cognitive impairment, IL-6 was not verified to contribute in the non-depressive group, but an association was identified in the depressive group." (PMID 34299040, 2021). "Moreover, we observed that the postmenopausal women with cognitive impairment had significantly higher E-DII scores and IL-6 levels." (PMID 34371834, 2021). "Studies showed that the levels of IL-6 and TNF-α were elevated in the brain and in cerebrospinal fluid (CSF) of AD patients, while IL-6 may be a predictor for the severity of cognitive defects." (PMID 34706756, 2021). "In addition, IL-6 mediates the activation of neuronal NADPH oxidase and cognitive impairment in old mice." (PMID 33059734, 2020). "Thus, pretreatment with Tan IIA significantly prevented cognitive impairment induced by CCL2 and inhibited the expression of IL-1β and IL-6." (PMID 32185196, 2020). "In an animal study, Sun and his colleagues found that Rehmannioside A could attenuate cognitive deficits in rats with VD through reducing the release of proinflammatory cytokines, including TNF-α, IL-1β, and IL-6." (PMID 32617097, 2020). "Interleukin-6 (IL-6) and tumor necrosis factor-α (TNF-α) have also been reported as inflammatory parameters, which are the important factors to lead to sarcopenia and the development of cognitive impairment." (PMID 32066390, 2020). "It is well established that inflammatory responses, including activation of glial cells and production of inflammatory cytokines such as IL-1β, IL-6, COX-2, iNOS, and TNF-α, induced by CCH could further result in neuronal cell death and cognitive deficits." (PMID 31900229, 2020).
Cognitive impairment (continued). "Proinflammatory cytokines IL-1β, IL-6, and TNF-α independently resulted in cognitive impairment." (PMID 32063834, 2020). "The synthesis and release of proinflammatory cytokines such as IL-1β, IL-6, and TNF-α contribute to cognitive impairment by affecting cognitive processes such as synaptic plasticity, neurogenesis, neuromodulation, memory consolidation, and long-term potentiation (LTP)." (PMID 31565046, 2019). "Activated glia stimulated by Aβ has been reported to upregulate the expression of several proinflammatory chemokines and cytokines including IL-1β, IL-6, and TNF-α, which could result in an increase of Aβ production, neuronal death, and cognitive deficits." (PMID 30871577, 2019). "In addition, HBO2T reversed the HAE-induced upregulation of brain levels of proinflammatory cytokines including IL-1β, IL-6, TNF-α, and IF-γ as well as cognitive deficits." (PMID 30515398, 2018). "Going beyond previous work, the present study took a novel methodological approach by examining the mediation of systemic inflammation (i.e., serum levels of IL-6, TNF-α and CRP) on age-related cognitive impairments (i.e., deficits in processing speed and short-term memory)." (PMID 30127734, 2018). "To determine whether the inflammatory cytokines was involved in the cognitive impairment of the diabetic rats, we examined TNF-α, IL-1β and IL-6 mRNA expression in the brain." (PMID 29867440, 2018). "IL-6 levels in PD-CI patients are strikingly enhanced comparing with those without cognitive impairment (P = 0.005)." (PMID 24884485, 2014). "We will determine whether the peripheral surgical wounding without the influence of general anesthesia can still induce cognitive impairment in aged TNF-α, IL-6, or CD33 knockout mice in our future studies." (PMID 24796537, 2014). "Moreover, we measured proinflammatory cytokines IL-1β, IL-6 and TNF-a concentration at a time when animals had significant cognitive impairments." (PMID 23613842, 2013). "Clinical studies aim to assess whether modulation of the IL-6 axis can impact positive and negative symptoms as well as cognitive deficits in patients with SCZ, supporting the concept of immunomodulatory strategies in the treatment of this disorder." (PMID 41007867, 2025). "However, plasma IL-6 concentration does not appear to correspond with MIA-induced cognitive deficits." (PMID 40419496, 2025). "Our results demonstrated that T3 treatment reversed cognitive impairment and increased Akt and GSK3 phosphorylation in the treated group, while also reducing microglial activation (Iba-1) and GFAP expression (reactive astrocytes), along with TNF-α, IL-6, and IL-1β levels in the hippocampus." (PMID 39513900, 2024). "In terms of sources, omega-3 s from both dietary and supplementation sources may have positive health benefits, additionally, supplementation studies appear to demonstrate more consistent reductions in inflammatory markers including IL-6 and TNF-α amongst populations with mild cognitive impairment." (PMID 38371504, 2024). "Increasing evidence suggests that flavonoids could ameliorate allergic inflammation by suppressing IL-4 and IL-13 production following the release of basophils and histamine, and improve the cognitive impairment of patients with neurodegenerative disease by inhibiting TNF-α and IL-6 release." (PMID 37292198, 2023). "In addition, proinflammatory cytokines (interleukin 1β (IL-1β), interleukin 6 (IL-6), and tumor necrosis factor α [TNF-α]) are markedly increased in patients with mild cognitive impairment and AD, suggesting that intrathecal inflammation precedes AD development." (PMID 37163443, 2023). "However, recent large-scale meta-analyses support the hypothesis of immune dysregulation in AD and mild cognitive impairment, reporting elevated peripheral levels of CRP, IL6 and IL1β in AD compared to controls." (PMID 37467176, 2023).